IL7R (interleukin 7 receptor)
Diseases named in the same sentence as IL7R in open-access papers (continued):
Sharing a sentence is not in itself a finding about the gene and the disease.
tumor (continued). "Establishment of the relationship between GPX4/A2AR and IL-7Rα–mediated signaling in naive and tumor antigen–experienced T cells warrants further investigation." (PMID 38441967, 2024). "Immunofluorescence staining of tumor tissues further confirmed the cell surface expression of IL7R (CD127) on macrophages and DCs, and the presence of pro-inflammatory CD127+ macrophages and DCs." (PMID 38424167, 2024). "Specifically, the complex formed by IL-7 with IL-7R-Fc has been shown to induce an anti-tumour response by increasing the infiltration of T cells into tumours through the CXCR3 chemokine signalling pathway." (PMID 38675377, 2024). "Conversely, CD52 and KRT19 were identified as predictive biomarkers linked to the tumour microenvironment (TME) of BC,39, 42, 43 whereas genetic variations in IL7R dramatically raised the susceptibility to BC in Chinese Han women." (PMID 39098994, 2024). "To determine the anti-tumor efficacy of rIL7, we first analyzed IL7R expression in the mouse tumor transplant model." (PMID 38424167, 2024). "This review aims to discuss the origin of IL-7 and its receptor IL-7R, its anti-tumour mechanism, and the recent advances in the application of IL-7 in tumour therapy." (PMID 38675377, 2024). "Further analysis of tumor-infiltrating transferred T cells as well as those in TDLNs at the end point revealed that the CUL5 KO T cells had significantly higher IL7R and GZMB expression levels than the NC cells." (PMID 38242867, 2024). "To improve the phenotype of tumor-directed T-cell therapy, we show that provision of cell-intrinsic IL7R-mediated signaling is preferable to activation of cells with exogenous IL7." (PMID 39186002, 2024). "This pathway specifically involves the IL7R gene, which is known to be related to tumor immunity and acts as a signal receiver that helps the immune system recognize and attack HCC cells." (PMID 39452074, 2024). "In our study, we observed that B7H3 IL7R-S CAR-T cells maintained the phosphorylation of STAT5 (pSTAT5) more effectively than did the other IL7R constructs, which correlated with the superior antitumor activity of IL7R-S in the tumor rechallenge assay." (PMID 38619641, 2024). "Using a model of functional antimelanoma memory, we found that high IL-7R expression selectively marks a CD8+ population in lymphoid organs that plays critical roles in maintaining tumor remission after immunotherapy or surgical resection." (PMID 37459511, 2023). "Recently, IL-7R agonists have been shown to drive the generation of a “stem-like” population of early memory/effector cells believed important for tumor suppression." (PMID 37874823, 2023). "The majority of the CD4 T cells in the HT-29 tumor cell killing assay were PD1+IL7R-CD107a+, resembling the phenotype of the intratumoral C1-PRF1 CD4 T-cell population identified by scRNAseq." (PMID 37185301, 2023). "Overall, T cells in the irradiated tumor had a more memory- or progenitor-like phenotype compared with the untreated tumor, with higher expression of genes encoding TCF-1 (TCF7), CD127 (IL7R), and L-selectin/CD62L (SELL)." (PMID 37209684, 2023). "We also identified genes encoding membrane receptors (IL7R, OSMR, EGFR) and transcriptional regulators (BNC2, BNC1, HMGA2, KLF7, NR3C1) as enriched in Basal tumours." (PMID 36944729, 2023). "The most intensively studied IL-7R agonist now in development is the PK-enhanced IL-7 efineptakin alfa, previously shown to suppress tumor growth in preclinical murine tumor models, both as monotherapy and in combination with a PD-1 CPI." (PMID 37874823, 2023). "IL7 exerts its biological functions primarily by activating the IL7 receptor (IL7R) to mediate various signaling pathways and shape tumor immunity." (PMID 37958451, 2023). "We also attempted to identify a rodent-specific IL-7R agonist from the same peptide sequence family as MDK1472/-703 to serve as a surrogate in mouse tumor models." (PMID 37874823, 2023).
tumor (continued). "Collectively, these experiments suggest that IL-7R is a functional marker of a tumor-specific memory/cytotoxic CD8+ T cell population with superior antitumor function." (PMID 37459511, 2023). "The six key-gene signature (ADRB2, DPYSL2, IL7R, LIMCH1, PIK3R1 and SOX2) has been shown to be associated with metastasis and progression of many tumor types through molecular experiments." (PMID 38057344, 2023). "Equally important, RG-108 treatment led to increased IL-7R expression and abrogated the difference in antitumor efficacy seen between IL-7Rlo and IL-7Rhi we previously found, leading to tumor clearance in 60% of the RG-108-treated IL-7Rlo T cell recipients." (PMID 37459511, 2023). "The absolute number of effectors PD-1+ CD8 T cells, defined as SLECs (KLRG-1+ / IL7Rα-) and MPECs (KLRG-1- / IL-7Rα+) were significantly augmented in tumor infiltrates of HVEM KO tumors compared to that of HVEM WT tumors." (PMID 37033927, 2023). "The IL-7Rhi memory/cytotoxic population is found in the tumor-draining lymph node and spleen early after priming and is functionally dependent on IL-7R signaling." (PMID 37459511, 2023). "Conversely, functional memory mice had a significant increase in the proportion of tumor-specific T cells marked by IL-7R compared with exhaustion." (PMID 37459511, 2023). "To determine if this expanding IL-7Rhi tumor-specific CD8+ population is functionally important for antitumor memory, we blocked IL-7R signaling both after initial tumor challenge (priming) or during functional memory rechallenge." (PMID 37459511, 2023). "Our results suggest that IL7R inhibits tumor growth by regulating the proportion of immune infiltrating cells in the tumor immune microenvironment." (PMID 35264973, 2022). "IL-7 receptor (IL-7R) mRNA has been seen in a variety of tumor cells, including breast, colon, lung, renal, and CNS." (PMID 35794603, 2022). "Tumor cell coculture reduced expression of the homeostatic cytokine receptor IL7R in both HER2-CAR and HER2-CAR TRX1 T cells." (PMID 36591284, 2022). "In the Cox regression multivariate analysis, IL-7R, mTOR, and tumour stage were the strongest predictors of survival." (PMID 35778432, 2022). "As for IL7R, interleukin-7 receptor, it plays an important role in tumor immunity through the conventional JAK/STAT pathway as well as endogenous competitive regulating RNA networks." (PMID 35092558, 2022). "NK subpopulations revealed a KIT+IL-7R+ progenitor subset that was suppressed within tumor but increased in patients who obtained good pathological response to NACT." (PMID 36253784, 2022). "Of PD-1+ CD8+ T cells within the tumor, IL7R and TCF7 expression was highest on CEFX-specific cells." (PMID 35584630, 2022). "CXCR3 ligands have been suggested to play an essential role in IL-7/IL-7Rα-Fc-mediated anti-tumor activity in lung cancer studies." (PMID 36479091, 2022). "Neutralizing CXCL9, CXCL10, or IFN-γ reduces CXCR3-expressing activated T cells infiltrating tumors and abrogates IL-7/IL-7rα-Fc-mediated tumor growth inhibition." (PMID 36479091, 2022). "For example, IL7R was down-regulated in LUAD tumor tissues from GSE10072, TCGA and GSE40791, but up-regulated in GSE68465." (PMID 35710585, 2022). "The IL7R expression was negatively correlated with tumor size and positively correlated with overall survival and progression-free survival in LUAD patients." (PMID 35264973, 2022). "Cox regression multivariate analysis show IL-7R, mTOR, and tumor stage were independent predictors of survival." (PMID 35778432, 2022). "The expression of IL7R was correlated with the tumor size, the IL7R expression in the T1 stage was significantly higher than in other T stages." (PMID 35264973, 2022).
tumor (continued). "Although the decreased IL-7R level after tumor removal or chemotherapy can be attributed to reduced tumor activity, reduced host immunity as a result of surgery or chemotherapy cannot be ruled out and warrants further research." (PMID 35159120, 2022). "This conclusion was also supported by Yin’s research, which said that high expression of IL7R can enhance anti-tumor immunity and indicate a better prognosis of HCC patients." (PMID 35092558, 2022). "IL-7Rα inhibits the growth of tumor cells by affecting the percentage of infiltrating cells in the tumor immune microenvironment." (PMID 36142322, 2022). "With increasing tumor size, the IL-7R level exhibited a decreasing trend and the CA19-9 level showed an increasing trend." (PMID 35159120, 2022). "In Section 3.2, the tumor-promoting effects of IL-7 and IL-7Rα and how they contribute to carcinogenesis have been described in detail." (PMID 36142322, 2022). "On the other hand, evidence has shown that the administration of IL-7/IL-7Rα-Fc inhibits tumor growth and prolongs survival in lung cancer by inducing afferent and efferent antitumor responses." (PMID 35794603, 2022). "A group of researchers demonstrated that therapy using an IL-7 complex, formed with an IL-7R-Fc, induced anti-tumor responses by increasing tumor infiltration of T cells through CXCR3 chemokine signaling." (PMID 34925323, 2021). "Collectively, these results indicate that the Rorα expressing IL-7R-positive immune cells limit CRC progression, as their loss augments tumour growth." (PMID 33535624, 2021). "For this reason, we evaluated the relation of TSLP, TSLPR, and IL-7R SNPs with CRC development based on the tumor location." (PMID 34573368, 2021). "Secondary alterations affecting cytokine signalling occurred in 37% iAMP21 of tumours (QBinomial = 2.2 × 10−3) involving IL7R, JAK2 or CRLF2 (including 3/5 cases of P2RY8-CRLF2 translocation)." (PMID 34753926, 2021). "In conclusion, we showed that IL-7R expressing cells in PBMC was detectable in early period during tumor formation in vivo." (PMID 34575268, 2021). "CCL20, MMP14, and PCDH7 were upregulated in LUAD tumor tissues and linked to poor clinical outcomes, while BTG2, CD69, GPC3, IL7R, and NMUR1 are the opposite." (PMID 34881236, 2021). "Altogether, this suggests that IL-7R signaling can activate and/or cooperate with a program involved in tumor spreading." (PMID 34907175, 2021). "Although the IL(R)-based signature exhibited powerful predictive ability, these signature members themselves (IL-7R, IL-5RA, IL-20RB, IL-11, and IL-22RA1) were rarely reported to be used to predict tumor prognosis." (PMID 34497605, 2021). "It was confirmed that IL-7R+ cells in PBMC were higher in tumor cell bearing mouse than PBS injected mouse." (PMID 34575268, 2021). "The results from IL7R homozygous mice would also be compatible with wild-type IL-7R acting as a tumor suppressor." (PMID 34907175, 2021). "TMRI16L and IL7R are also related to tumor immunity, which regulate tumors through the typical JAK/STAT pathway and the endogenous competitive ceRNA network." (PMID 33681288, 2020). "Conversely, the expression of cytokine receptor-encoding genes IL7R, IFNGR1, IL18R1, and potentially IL23R (p = 0.065), was downregulated in HCC tumor-infiltrating MAIT cells." (PMID 32849590, 2020). "We found that CXCL12 and IL7R were novel therapeutic targets for LIHC, which correlated with somatic mutations and tumor immunological microenvironment modulation." (PMID 33344233, 2020). "Constitutive IL7Rα/IL7Rα signaling finally contributes to cellular transformation, increased proliferation and tumor formation." (PMID 31817502, 2019). "Collectively, these data suggest that IL-7 and/or IL-7Rα are promising targets of inhibiting tumor metastasis." (PMID 31061414, 2019). "The expression of tumor proliferation indication Ki-67 was also inhibited by knockdown of Lnc-IL7R in vivo." (PMID 29720427, 2018).
tumor (continued). "Given the tumorigenic role of Lnc-IL7R in vitro, we next estimated the efficiency of Lnc-IL7R knockdown for tumor progression by lentivirus vector of siRNA-Lnc-IL7R in vivo." (PMID 29720427, 2018). "In conclusion, we confirmed the relationship between enhanced IL-7R signaling, tumor aggressiveness and steroid-resistance in lymphoid malignancies." (PMID 28878234, 2017). "A7R-ADC-SN-38 showed a stronger cytotoxic effect than CPT-11, suggesting that this ADC would also be effective against circulating IL-7R-positive tumor cells." (PMID 28878234, 2017). "Knockdown of IL-7R attenuated both cell growth kinetics in vitro and tumor growth in mice (upon subcutaneous injection, for four of the five cell lines) relative to control cells." (PMID 28878234, 2017). "In sharp contrast, donor CD4+ T cells downregulated IL-7Rα upon antigen recognition in unconditioned tumor-bearing mice and IL-7Rα remained suppressed in these mice." (PMID 28939858, 2017). "We observed IL-7R expression in both malignant lymphoid cells and metastatic solid tumor cells and found that abrogation of this expression reduced tumor aggressiveness." (PMID 28878234, 2017). "Alternatively, tumor-specific donor T cells can be engineered to overexpress IL-7Rα to allow them respond to exogenous IL-7 after transfusion." (PMID 28939858, 2017). "A7R was distributed throughout the entire tumor area, and the ADCs bound to and were internalized by IL-7R-positive CYG82 cells." (PMID 28878234, 2017). "Here, we identified a novel relationship between IL-7R signaling and steroid-resistance, and showed that an anti-IL-7R antibody conjugated with SN-38 (A7R-ADC-SN-38) has strong anti-tumor effects against both parental and steroid-resistant malignant cells." (PMID 28878234, 2017). "This conclusion is supported by the fact that rIL-7-induced OT-I expansion and subsequent TM differentiation occurred efficiently in Rag-/-IL-7R-/- mice while tumor rejection failed." (PMID 27447484, 2016). "Several studies have demonstrated that IL-7R is involved in proliferation and migration of tumor cells." (PMID 27821177, 2016). "As compared to untreated controls, OT-I cells strongly delayed tumor growth in Rag-/-IL-7R-/- recipients similar to what we had observed in Rag-/- mice." (PMID 27447484, 2016). "Compared with adjacent tissues, significantly higher expression of IL-7R was found in HBV-related tumor tissues (χ2 = 27.2, p < 0.01)." (PMID 27821177, 2016). "IL7R, a receptor of interleukin 7, can influence the malignancy proliferation by the tumor microenvironment." (PMID 27821810, 2016). "In contrast to the 100% protection in WT mice, combination therapy failed to cure Il7r−/− tumour-bearing mice, which rapidly died within 20 days post-tumour inoculation, reflecting a critical role of IL-7-IL-7Rα signalling in combination therapy." (PMID 27498556, 2016). "Since both Ifngr1−/− and Il7r−/− mice are incapable of eliminating primary tumours upon combination therapy, we contemplated memory cell expansion is defective in these KO mice." (PMID 27498556, 2016). "Combination therapy-improved survival of tumour-bearing mice that received WT total T cells but remained largely ineffective in those with adoptively transferred Il7r−/− or Ifngr1−/− total T cells." (PMID 27498556, 2016). "To assess if combination therapy-improved mouse survival also depends on IL-7 and IFN-γ signalling in T cells, we followed long-term survival of CD45.1 tumour-bearing mice that were infused with WT, Ifngr1−/− or Il7r−/− total T cells." (PMID 27498556, 2016). "In fact, IL-7R signaling by host cells is crucial for tumor rejection after CD8+ T cell transfer and rIL-7 therapy." (PMID 27447484, 2016). "In our future studies, we propose to analyze IL-7Rα expression in human tumours treated with immune checkpoint therapy." (PMID 27498556, 2016).
tumor (continued). "In the current study we provide evidence that CD8+ T cell-mediated tumor rejection in response to recombinant IL-7 (rIL-7) therapy is strictly dependent on IL-7R+ host cells." (PMID 27447484, 2016). "Increased expression of IL-7R was also found to prevent apoptosis and promote proliferation and migration of tumor cells by activating intracellular pathways and upregulating the associated downstream molecules via binding to its ligand, IL-7." (PMID 27821177, 2016). "As a result, further research studies are needed to justify the function status of IL-7R expressed on tumor cells." (PMID 25955647, 2015). "Encouragingly, the in vivo immune stimulation activities of the Fc-IL-7/Neo-7s also translated into anti-tumor activities where the efficacy of tumor growth delay was correlated with the binding affinities to IL-7Rα determined in the yeast display and SPR assays." (PMID 41542752, 2026). "Another study found that CD69 could serve as a prognostic marker for SKCM, influencing immune response through interactions with genes like PTPRC and IL7R, and impacting tumor progression by regulating the tumor immune microenvironment." (PMID 40547036, 2025). "Also, the IL-7Rα-Tris-CAR-T cells induce selective toxicity to tumor cells, and the IL-7/IL-7Ra-mediated signaling promotes the proliferation and survival of T cells." (PMID 41208963, 2025). "Mutation-associated neoantigen (MANA) -specific CD8+ tumor-infiltrating lymphocytes (TIL) have been shown to express high levels of CXCL13 and CD39 (ENTPD1), and low IL-7 receptor (IL7R) levels in many cancer types, but their collective relevance to T cell functionality has not been established." (PMID 39900903, 2025). "IL7R signaling contributes to immune evasion by promoting M0 macrophage polarization toward an immunosuppressive M2 phenotype, suppressing cytotoxic T—cell activity, and enhancing tumor cell survival through JAK—STAT3 pathway activation." (PMID 40165301, 2025). "In the subcutaneous xenograft model, Il7r-KO cells exhibited significantly suppressed tumor growth." (PMID 41360767, 2025). "In the context of HGGs, IL7R expression may play a role in tumor growth and immune evasion, making it a promising target for therapeutic intervention." (PMID 40165301, 2025). "In this context, tumor cells with high IL-7R expression may co-opt IL-7 signaling to promote the enrichment of immunosuppressive TAM via CXCL1-dependent mechanisms; this process counteracts the potential immunostimulatory effects of IL-7." (PMID 41360767, 2025). "Tumor effector memory CD8 T cells demonstrated overexpression of CCR7, IL7R, and CXCR4, which are associated with a naïve-like T cell state and inversely associated with T cell polarization and effector T cell function, as well as TXNIP, which negatively regulates T cell proliferation." (PMID 40848148, 2025). "IL7R also displayed a significant decline in expression (p = 0.000507), suggesting that the diminished immune signaling pathways may facilitate tumor progression in the CNS environment." (PMID 40725191, 2025). "To validate the protein expression of IL7R, we performed immunohistochemistry (IHC) on a tissue microarray of 15 human cancer types, which revealed positive staining of IL7R in the majority of tumor tissues." (PMID 38424167, 2024). "Notably, low expression of IL7R has been correlated with increased tumor growth and lower survival rates." (PMID 39911484, 2024). "Importantly, we show that >95% of tumor-specific CD8+ T cells in the postimmunotherapy tumor-draining lymph node express high levels of IL-7R, which is otherwise sparsely expressed in the lymph node by nonantigen-specific cells." (PMID 37459511, 2023). "The SLECs PD1+ CD8 T cell population (KLRG-1+ / IL-7Rα-) that clonally expanded in response to the tumor was restricted to CD8 T cells co-expressing PD-1, as SLECs PD-1- CD8 T cells were almost undetectable in the tumor infiltrates of both HVEM WT and HVEM KO tumors." (PMID 37033927, 2023).